APC (APC regulator of Wnt signaling pathway)
Diseases named in the same sentence as APC in open-access papers (continued):
Sharing a sentence is not in itself a finding about the gene and the disease.
colorectal adenoma (99 papers, 2000 to 2026). An adenoma that arises from the colon or rectum. "For WGS, fifty-seven colorectal adenomas or carcinomas and six normal colon mucosa samples were analyzed from eighteen patients with APC variants fitting SBS88 or SBS18 (cases) and nine patients without these variants (controls)." (PMID 38238650, 2024). "NGS showed somatic APC variants fitting SBS88 or ID18 in at least one colorectal adenoma or carcinoma in 29% of patients." (PMID 38238650, 2024). "The Wnt/β-catenin pathway plays a key role in the onset of colorectal adenoma; in particular, intestinal cells first acquire loss-of-function mutations in the APC gene that induce the formation of adenomas." (PMID 39200196, 2024). "Since APC mutation occurs in >80% sporadic colorectal adenomas and adenocarcinomas, it is possible that most of the cancer tissues we studied have APC mutations." (PMID 39413959, 2024). "FAP patients were defined as having more than 100 cumulative colorectal adenomas and/or having a known germline pathogenic variant in the APC gene." (PMID 39046601, 2024). "In 110 patients, at least one colorectal adenoma or carcinoma harbored an APC variant that fits with one of the colibactin-associated mutational signatures." (PMID 38238650, 2024). "Mutations in the adenomatous polyposis coli (APC) gene occur early in approximately 70% of patients with colorectal adenomas." (PMID 37763765, 2023). "As mutations in the adenomatous polyposis coli (APC) tumor suppressor gene have been frequently detected in colorectal adenomas, the APC gene is considered a gatekeeper in colorectal carcinogenesis." (PMID 36826061, 2023). "APC: APC is a tumor suppressor gene, and the inactivation of APC due to somatic mutations causes colorectal adenomas and cancers." (PMID 37193451, 2023). "Obesity is positively associated with increased APC mutations, reported as gatekeepers in the early stages of the colorectal adenoma-carcinoma sequence." (PMID 35062912, 2022). "About 80% of colorectal adenomas and adenocarcinoma have APC gene deletion or inactivation mutations, and the mutation runs through the whole process of carcinogenesis." (PMID 33836681, 2021). "In a previous study of FAP-related colorectal adenomas, only 3/13 (23%) truncating somatic APC variants were indels." (PMID 34843512, 2021). "Niku and colleagues found that Western diet accelerates the formation of colorectal adenomas, which was accompanied by the loss of APC gene heterozygosity." (PMID 33897888, 2021). "Numerous studies to date have reported a correlation between locations (genotype) of APC gene variants and number of colorectal adenomas and concomitance of extracolonic lesions (phenotype)." (PMID 34185173, 2021). "Mutation of the tumor suppressor gene APC is detectable in 70% of benign colorectal adenomas, resulting in the inactivation of APC in the majority of colorectal adenomas." (PMID 34200820, 2021). "Familial adenomatous polyposis (FAP) is caused by a mutation in the adenomatous polyposis coli (APC) gene and characterised by the development of hundreds to thousands of colorectal adenomas." (PMID 33376109, 2020). "All FAP patients carry inactivating mutations of the adenomatous polyposis coli (APC) tumour suppressor gene, and the gene is also mutated in 70–80% of sporadic colorectal adenomas and carcinomas." (PMID 31414579, 2019). "In both normal tissues compared with colorectal adenoma and colorectal adenocarcinoma analyses, somatic mutations were observed in the tumor suppressor gene APC (Adenomatous polyposis coli) in eight out of ten patients." (PMID 31336886, 2019).
colorectal adenoma (continued). "We identified genes with somatic mutations in the normal-colorectal adenoma samples, APC, CTNNB1, LRP5, FBXW7, and ATM, which overlapped with the TCGA data." (PMID 31336886, 2019). "Dnmt3a suppresses K-Ras-driven lung tumor progression, whereas Dnmt3b is pro-tumorigenic in APC-deficient colorectal adenomas." (PMID 28425913, 2017). "Approximately 70%–80% of sporadic colorectal adenomas and carcinomas have somatic mutations that inactivate APC in Western countries." (PMID 27578919, 2016). "A total of 419 APC mutation-positive patients were included, of which 188 (44.9 %) had more than 100 colorectal adenomas." (PMID 26880076, 2016). "Carriers of mutations in the APC gene develop multiple colorectal adenomas and consequently have a high risk of developing CRC." (PMID 26880076, 2016). "In colorectal adenomas and carcinomas where both APC alleles are defective, destruction of the free pool of beta-catenin is impaired, and active beta-catenin accumulates in the cytoplasm and nucleus to reactivate Wnt/beta-catenin target genes in CRC." (PMID 27578919, 2016). "In conclusion, our data represent the most extensive evaluation of the APC gene in colorectal adenomas and carcinomas from Jewish carriers of the c.3920T>A mutation reported to date." (PMID 24416237, 2014). "One study of young North American patients of various ethnic backgrounds with ten or fewer colorectal adenomas reported finding protein-truncating germ line variants within the APC open reading frame in 10 of 74 (13.5%) patients." (PMID 24416237, 2014). "Mutation of the APC gene causes abnormal crypt production, disorientation of the crypts, leading to colorectal adenomas." (PMID 24205248, 2013). "Mutations in CTNNB1 (β-catenin) have been reported as an alternative to APC mutations and were found more frequently in small colorectal adenomas." (PMID 22848674, 2012). "In this Norwegian case-control study, the KAM cohort, we used direct sequencing of the APC MCR to evaluate the mutational spectra of the gene in relation to smoking history in both colorectal adenomas and carcinomas." (PMID 16545110, 2006). "The KAM study is to the best of our knowledge the first study to evaluate the association between colorectal adenomas, APC mutations and smoking history, and also to evaluate the complete mutational spectra of APC in CRC cases in relation to smoking history." (PMID 16545110, 2006). "APC mutations are present in about 80% of sporadic colorectal adenomas and cancers, while in recent studies, APC mutations have been rare in SAs." (PMID 12838317, 2003). "For 13 mutations, predicted to result in null alleles or truncated APC proteins, we correlated density and distribution of colorectal adenomas with the predicted functional effects of the mutation." (PMID 10646887, 2000). "Additionally, mutations in the APC gene, frequently observed in colorectal adenomas, lead to constitutive activation of the Wnt/β-catenin pathway." (PMID 41195400, 2025). "APC mutations are frequently found in colorectal adenomas, which are precancerous growths." (PMID 40943055, 2025). "Mutations in the APC gene have a strong relationship with colorectal adenomas." (PMID 35285179, 2022). "However, development of most colorectal adenomas and carcinomas does involve somatic mutations of APC." (PMID 35297393, 2022). "Indeed, an early transformation of epithelial cells involves a mutation in the adenomatous polyposis coli (APC) or Axin2 (in 70% of colorectal adenomas), followed by a long-term activation of β-catenin." (PMID 35889921, 2022). "APC mutation can be detected in the majority of colorectal adenomas (70%)." (PMID 34200820, 2021). "Loss of function mutation in the APC gene is associated with an accumulation of intracellular beta-catenin protein, which leads to loss of control of normal beta-catenin signaling, which promotes colorectal adenoma formation." (PMID 33511474, 2021).
colorectal adenoma (continued). "The mutation of the APC gene contributes to the abnormal activation of the Wnt/β‐catenin signalling pathway, which results in interference with the expression of multiple genes, initiating colorectal adenoma in Apcmin/+ mice." (PMID 34709758, 2021). "Since arginine metabolism was well accepted to play an important role in cancer cells development, we hypothesis that enhanced metabolism of arginine in patients with APC-mutated colorectal adenoma was probably due to other microbiomes." (PMID 31892851, 2020). "Finally, E2F4 was found to be overexpressed, phosphorylated and nuclear localized in epithelial cells from human colorectal adenomas exhibiting mutations in APC and KRAS or BRAF genes, known to deregulate GSK3/β-catenin and MEK/ERK signaling, respectively." (PMID 23919615, 2013). "Finally, we show that E2F4 is overexpressed, phosphorylated and localized in the nucleus of epithelial cells from colorectal adenomas exhibiting APC and KRAS or BRAF mutations." (PMID 23919615, 2013). "MYH deficiency causes colorectal adenomas through somatic hypermutation of the APC and K-ras genes." (PMID 17505512, 2007). "In serrated adenoma (SA), a newly recognised subtype of colorectal adenoma, APC mutations are uncommon, and the contribution of β-catenin to tumorigenesis remains unclear." (PMID 12838317, 2003). "However, certain pathogenic APC variants are associated with the density of colorectal adenomas and the occurrence of extracolonic manifestations (e.g., fundic gland polyposis, duodenal adenomas, osteomas, desmoid tumors, and the CHRPE phenotype) in patients with FAP." (PMID 41214301, 2026). "Thus, APC mutations are most likely associated with the initiation of colorectal adenoma." (PMID 41488735, 2025). "On the other hand, loss of αE-catenin was reported to suppress colorectal adenomas induced by APC loss-of-function, an effect that could be mediated by the Rho-Rho kinase signalling-dependent cell death elicited by the loss of the CCC in an APC mutant background." (PMID 31697683, 2019). "Genetic mutations in the tumor suppressor gene APC and the oncogene KRAS are an initial event in the colorectal adenoma-carcinoma sequence." (PMID 41488735, 2025). "In conclusion, our study aims to enhance the comprehension of the pathogenesis in colorectal adenomas (CRAs) and to propose the utilization of APC and β-catenin as markers in clinical settings." (PMID 39200196, 2024). "As shown in the literature, induction of oncogenic APC expression in the mouse intestine leads to the development of colorectal adenomas and carcinomas with features akin to those observed in human colorectal lesions." (PMID 37468468, 2023). "APC mutations are present in 80% of CRC cases and play a role in the initiation of colorectal adenoma development." (PMID 37483596, 2023). "Our results showed that APC, CTNNB1, IGF1, and KLF5 were frequently mutated in normal-colorectal adenoma." (PMID 31336886, 2019). "The frequency of APC promoter hypermethylation was significantly higher in colorectal adenoma than in normal colorectal tissue, OR was 5.76, 95% CI, 2.45-13.56; p<0.0001, I2=0%." (PMID 28515349, 2017). "Accordingly, most of colorectal adenomas analyzed herein exhibited KRAS (G12D, G13D, Q61H) or BRAF (V600E) activating mutations, in combination with APC inactivating mutations (exon 15)." (PMID 27582544, 2016). "Identification of APC mutations and loss of heterozygosity (LOH) in approximately half of sporadic colorectal adenomas and majority of adenocarcinomas indicates that APC inactivation is an early event in tumor progression (i.e. initiation)." (PMID 23302090, 2013). "Somatic mutation frequencies and spectra at APC, K-ras and BRAF were, however, similar to those in sporadic colorectal adenomas." (PMID 17505512, 2007).
colorectal adenoma (continued). "Mutations near the 5’ end of APC (upstream to codon 157) or downstream codon 1595, including the alternatively spliced region of exon 9, are correlated with a milder form of FAP termed Attenuated FAP (AFAP), characterized by less than 100 colorectal adenomas." (PMID 40695959, 2025). "Although the APC mutation rates in intestinal-type non-ampullary duodenal adenoma are similar to colorectal adenoma, APC mutations have been found to be rarer in advanced duodenal carcinoma." (PMID 35778698, 2022). "A subset of patients with multiple colorectal adenomas and no APC germline variants have been found to carry biallelic variants in the base excision repair gene MUTYH (MIM# 604,933), causing MUTYH-associated polyposis (MAP; MIM# 608,456)." (PMID 33683519, 2022). "The somatic mutational profile of colorectal pre-cancerous lesions in FAP was recently investigated in a study on 25 colorectal adenomas and adjacent normal mucosa from 12 FAP patients with confirmed germline APC gene mutations through whole-exome sequencing (WES)." (PMID 33923068, 2021). "Interestingly, the position c.4348C>T (p.R1450*) of the APC gene was found in 2 out of 11 patients in the matched normal-colorectal adenoma tissue." (PMID 31336886, 2019). "Finally, the existence of genes, other than APC and MUTYH, susceptible to colorectal adenomas and cancer cannot be excluded." (PMID 20649969, 2010). "Genetic testing for MUTYH mutation has been recommended for all patients who have tens to hundreds of colorectal adenomas with no identified germline mutation in the APC gene and with a family history compatible with an autosomal recessive mode of inheritance." (PMID 19822006, 2009). "In a large screening of 453 APC-negative patients with more than five colorectal adenomas, it was found that pathogenic mutations were initially found in 74 patients without extra-digestive tumors (22.5%) and subsequently in 75 at-risk relatives." (PMID 19822006, 2009). "In addition, an epi-genetic change, i.e. promotor hypermethylation of the APC gene that leads to impaired APC function has been observed in 18% of sporadic colorectal adenomas and carcinomas." (PMID 16356174, 2005). "Moreover, NSAIDs appear to inhibit the initial stages of the colorectal adenoma-carcinoma sequence, suggesting a link to the APC/β-catenin/TCF pathway (Wnt-signalling pathway), and the colonic polyps of patients treated with NSAIDs demonstrate reduced nuclear accumulation of β-catenin." (PMID 18257933, 2008). "APC and KRAS are observed in colorectal adenoma and carcinoma with the rate of 40–80% and they play a role in early steps of carcinogenesis." (PMID 25945089, 2015). "Indeed, the findings from the database searches of Oncomine and cBioPortal show decreased expression of both APC and N‐WASP in colorectal adenomas and carcinomas, and that lower N‐WASP expression is associated with poorer survival." (PMID 29672847, 2018). "In our study, the heterozygous novel large deletion of APC gene in this Chinese family manifests with colorectal adenomas (polyps) without any extra-colonic manifestations." (PMID 27391059, 2016). "Recently, patients with multiple colorectal adenomas and also patients with FAP but without detectable germline APC mutations have been found to carry biallelic mutations in the base-excision-repair gene MUTYH (MYH)." (PMID 19531215, 2009). "Recently, biallelic mutations in MUTYH have also been identified in patients with multiple colorectal adenomas and in APC-negative patients with FAP." (PMID 19531215, 2009). "Loss of both alleles of the tumour suppressor gene Adenomatous Polyposis Coli (APC) is believed to occur prior to development of the benign precursor lesion of colorectal cancer (CRC), the colorectal adenoma (or polyp), in the majority of cases of sporadic colorectal carcinogenesis." (PMID 15188006, 2004). "APC c.5465T>A, though not disrupting the Wnt/β-catenin signaling pathway, may still promote colorectal adenoma formation." (PMID 41164816, 2025).
lung carcinoma (99 papers, 2004 to 2025). "The third case study focused on the APC gene, which is known to lead to a predisposition to colorectal and lung cancers." (PMID 37195695, 2023). "In terms of lung cancer, the aberrant methylation status of the APC and CDH13 promoters was associated with lung cancer risk." (PMID 35677637, 2022). "Partial loss of CH25H expression occurs in human intratumoral APC and is associated with lung cancer growth and progression." (PMID 36333297, 2022). "These associations include APC/CDC20 for EML4-ALK fusions in lung cancers, SPOP for NUP98-NSD1 and BCR-ABL fusions in LAML, and FBW7 (or FBXW7, F-box and WD repeat domain containing 7) for CCDC6-RET fusions in thyroid carcinomas (THCAs)." (PMID 34795215, 2021). "In the present study, we applied anti-DKK2 antibody to lung cancer mouse models driven by APC mutation." (PMID 31372243, 2019). "We also found significant upregulation of Dkk2 expression in human lung cancer tissues with APC mutations." (PMID 31372243, 2019). "APC expression in lung cancer are associated with survival time and is also related to cancer metastasis." (PMID 30591011, 2018). "In support of this theory, the APC/C was recently implicated in cancer cell dormancy and protection against drug-induced apoptosis in lung cancer cell lines." (PMID 27655696, 2016). "Although mutations of APC or β-catenin are infrequent in lung cancer, hyperactivation of the Wnt pathway, as evidenced by transcriptional overexpression of Wnt-responsive genes, has been documented in samples from aggressive lung adenocarcinomas." (PMID 26787475, 2016). "β-Catenin, as an important component of both adherens junctions and Wnt signaling pathway, was believed to be translocated into nucleus by its exon mutation and/or APC mutation in various tumor type except lung cancer." (PMID 25396757, 2014). "APC mutations are present but infrequent in human lung cancer, and we detected the intracellular localization of β-Catenin mainly on cytoplasmic membrane and cytoplasm in rest A549 cells." (PMID 24312384, 2013). "Although increased levels of β-catenin have been reported in different types of lung cancers, mutations of APC and β-catenin are rare in lung cancers." (PMID 16438732, 2006). "Similarly, methylation of the APC gene is also associated with lung cancer occurrence, with hypermethylation of the APC gene promoter detectable in both lung cancer tissues and patient plasma." (PMID 41394878, 2025). "We found significant upregulation of Dkk2 expression in APC-mutated lung cancers." (PMID 31372243, 2019). "Interestingly, APC mutations in lung cancer co-occurred with KRAS mutations in NSCLC, including adenocarcinoma and SCCs26." (PMID 31372243, 2019). "However, the diagnostic role of the methylation status of the APC gene in lung cancer lacks quantitative assessment." (PMID 24661338, 2014). "Monitoring the methylation status of the APC gene aids in the early diagnosis of lung cancer, especially for early lesions, which are difficult to detect through imaging examinations." (PMID 41394878, 2025). "APC methylation was evident in samples of sputum from lung cancer patients, emphasizing the potential of APC methylation as an early detection biomarker." (PMID 40191732, 2025). "Based on research, APC is related to lung cancer types (sporadic and familial), which are thought to suffer from a higher incidence due to an allelic loss." (PMID 37901797, 2023). "In light of these findings, the repressive function of APC in cancer would provide an attractive therapeutic target for lung cancer by boosting its function and using it as a biomarker." (PMID 37901797, 2023). "Detection of APC and RASSF1a promoter methylation independently predicted disease-specific mortality in lung cancer patients; these results are in line with our finding regarding the prognostic value of APC methylation in plasma-cfDNA." (PMID 35538556, 2022).